EGF (epidermal growth factor)
Diseases named in the same sentence as EGF in open-access papers (continued):
Sharing a sentence is not in itself a finding about the gene and the disease.
gastric cancer (continued). "We found that the variant genotype of EGF rs2237051 AG/GG is associated with an increased risk of intestinal gastric cancer and the variant genotype of EGF rs3733625 AG/GG is associated with a decreased risk of intestinal gastric cancer, compared with their wild-type homozygotes." (PMID 23420566, 2013). "In conclusion, our study shows that the two polymorphisms (rs2237051 and rs3733625) in the EGF gene may play a role in gastric cancer susceptibility and that drinking status may be a modulating factor." (PMID 23420566, 2013). "This may explain the correlation between the SNP rs2237051 of the EGF gene and risk of gastric cancer." (PMID 23420566, 2013). "Gastric cancer cells are known to highly express EGF mRNA, and intraperitoneal injection of bevacizumab significantly inhibited peritoneal metastasis and reduced malignant ascites in tumor-bearing mice." (PMID 40535136, 2025). "After identifying these prognostic genes, including CPZ, CTHRC1, DKK1, EGF, and GPC3, we will explore their specific impact on gastric cancer progression, as well as the molecular mechanisms underlying it, particularly the CPZ." (PMID 40296906, 2025). "In gastric cancer, Tspan8 was found to be positively modulated by EGF in a dose- and time-dependent manner, and silencing Tspan8 diminished the effects of EGF on cell proliferation and invasion." (PMID 38389703, 2024). "In gastric cancer cell, epidermal growth factor (EGF) regulates the expression of ATXN2L through the PI3K/Akt signaling pathway, thereby increasing the formation of SGs." (PMID 37179344, 2023). "Blocking HER2 activation using trastuzumab effectively abolished EGF-induced nuclear localization of SHCBP1 in gastric cancer cells." (PMID 35013128, 2022). "It is surprising to observe that BB94 also reduced DNA synthesis induced by exogenous EGF in gastric cancer cells." (PMID 34658851, 2021). "For example, Lin’s study showed ATXN2L upregulated by epidermal growth factor promotes gastric cancer cell invasiveness." (PMID 33776902, 2021). "At present, inhibitors targeting vascular endothelial growth factor (VEGF), epidermal growth factor (EGF), and tyrosine kinase have been successfully developed, showing significant curative effects on gastric cancer." (PMID 35096975, 2021). "When TSPAN8 was knocked down, the effect of EGF on promoting gastric cancer cell proliferation and invasion was attenuated." (PMID 34222025, 2021). "The changes in gene expression after treatment of the gastric cancer cell lines with EGF, cetuximab, trastuzumab or afatinib for 4 or 24 h were analyzed by RNA sequencing." (PMID 33115415, 2020). "EGF-conjugated chitosan NPs were crosslinked with tripolyphosphate (TPP) and curcumin, a photosensitizer, to generate curcumin-encapsulated and EGF-conjugated chitosan/TPP NPs to treat MKN45 human gastric cancer cells." (PMID 33121022, 2020). "The interaction between interleukin 1 α (IL-1α) and the EGF/receptor system stimulates the development of gastric cancer." (PMID 33167519, 2020). "EGF induces both expression of NRP-1 and VEGF, suggesting that the regulation of NRP-1 expression in gastric cancer is closely related to the EGF/EGFR system." (PMID 33167519, 2020). "A time-resolved analysis of downstream intracellular kinases following EGF, cetuximab, trastuzumab and afatinib treatment was performed by Luminex analysis in the gastric cancer cell lines Hs746T, MKN1, MKN7 and NCI-N87." (PMID 33115415, 2020). "Especially the role of HER-2 has been described as a keystone in EGF-mediated growth activation in breast or gastric cancer." (PMID 31488078, 2019). "Knockdown of NEDD4 severely impaired EGF-stimulated gastric cancer cell migration and invasion, suggesting that NEDD4 mediates migration and invasion signaling of EGFR." (PMID 29455656, 2018). "In the process of gastric cancer cell migration, EGF activates EGFR, which through the combination of Grb2 and DENND1A plays a role in target molecule activation and targeted recruitment." (PMID 30524285, 2018).
gastric cancer (continued). "In summary, we confirmed that EGF-induced activation of Rab35 in gastric cancer cells is regulated by DENND1A in this study." (PMID 30524285, 2018). "In summary, the only RTKs that were influenced by trastuzumab, afatinib, and EGF in the gastric cancer cell lines were the HER receptors." (PMID 29325228, 2018). "Consistent with these research results, our study in gastric cancer also showed that EGF stimulation can also promote the activation of Rab35, and thus promote BGC823 cells migration." (PMID 30524285, 2018). "We used the ‘spheroid colony formation’ method to identify gastric cancer stem-like cells (GCSLCs) in this study, which involves culturing potential CSCs with serum-free medium containing EGF and bFGF." (PMID 28446252, 2017). "Several studies indicated an association with advanced disease, metastatic disease and poor prognosis, while in early gastric cancers, per trend a smaller percentage of EGF-positive tumours was reported." (PMID 27933395, 2017). "Our results indicate that EGF stimulation has a similar effect on CREB activity in gastric cancer cell lines." (PMID 29237412, 2017). "The expression of AREG, EGF, HB-EGF and TGFα in gastric tumours and body fluids of gastric cancer patients has been analysed in multiple studies." (PMID 27933395, 2017). "Human Epidermal Growth Factor (Her-2/neu) has strong therapeutic implications in certain cancers like breast and gastric cancer." (PMID 27821098, 2016). "Another phenomenon we noticed here was that, in serum-starved conditions, CD24-knockdown cells had lower EGFR expression compared to control cells, and such difference was apparent before and after the gastric cancer cells were stimulated with EGF." (PMID 26830684, 2016). "Together, these data point to the ability of Arf6/ERK-dependent mechanism that leads to increased EGF-induced EMT of gastric cancer cells by inhibiting Wnt5a transcriptional expression." (PMID 25779663, 2015). "Although the current study has contributed to the mechanistic understanding the role of Wnt5a in EGF-induced gastric cancer cell EMT, the issue as to how Wnt5a precisely regulates EMT in gastric cancer cells is unlikely to be settled in this paper." (PMID 25779663, 2015). "Although the proposal that Wnt5a increases cell migration is compatible with its capacity to increase Arf6 activity in melanoma cells, we have limited knowledge concerning regulation of Wnt5a expression by EGF/Arf6 signaling in gastric cancer cells." (PMID 25779663, 2015). "Here, we show that downregulation of Wnt5a mRNA and protein by EGF is necessary for EGF-induced EMT in gastric cancer SGC-7901 cells." (PMID 25779663, 2015). "We here provide evidence that Wnt5a is a downstream mediator of EGF signaling in gastric cancer cells suggesting a primary effect of Wnt5a on reducing gastric cancer cell EMT." (PMID 25779663, 2015). "In the present study, we provide evidence that inhibition of Wnt5a expression is essential for EGF-induced EMT program in gastric cancer cells." (PMID 25779663, 2015). "Together, in the present study, we uncovered an essential role of Wnt5a in regulating EGF-induced gastric cancer cell EMT." (PMID 25779663, 2015). "Mounting evidences have demonstrated that the EGF plays a critical role in malignant transformation, tumor growth and progression and over-expression of EGF has been found in advanced gastric cancers." (PMID 25729328, 2014). "Both gastric ADAM17, and EGFR ligands HB-EGF, amphiregulin and EGF, are increased in patients with H. pylori infection and/or gastric cancer and are likely to contribute to epithelial hyperplasia." (PMID 25437333, 2013). "This provided further evidence of the inhibition of PKG II on EGF-induced migration of gastric cancer cells." (PMID 23613900, 2013). "In human gastric cancer, studies have demonstrated that epidermal growth factor (EGF) stimulates uPAR expression via the ERK pathway, sequentially increasing cell invasion." (PMID 26889270, 2013).
gastric cancer (continued). "Epidermal growth factor (EGF) is critical in cancer progression and various genotypes of the EGF gene have been reported to be correlated with susceptibility to gastric cancer; however, the results are unclear." (PMID 23420566, 2013). "The present study confirmed that in the gastric cancer AGS cell line, EGF caused Tyr1173 phosphorylation of EGFR and the consequent activation of the key components of the PI3K/Akt-mediated pathway, including PI3K, Akt, mTOR and NF-κB." (PMID 24273605, 2013). "Previous studies have reported that the EGF +61 (A/G) single-nucleotide polymorphism (SNP) in the 5′UTR of the EGF gene (SNP rs444903) is associated with various carcinomas, including gastric cancer." (PMID 23420566, 2013). "In this paper, we investigated the action of PKG II on EGF-induced migration activity of gastric cancer cell line AGS." (PMID 23613900, 2013). "Gastric carcinoma-derived MKN1 cells were chosen to examine the EGF response because of their amenable morphology, detailed characterization, widespread use and high level EGF receptor expression." (PMID 23028903, 2012). "The presence of EGF in gastric cancer is correlated with the degree of gastric wall invasion and lymph node metastasis." (PMID 19773760, 2009). "In our study, NRP-1 mRNA expression was induced by EGF treatment at 24 h in three different gastric cancer cell lines (AGS, NCI-N87, and ST-2)." (PMID 12618892, 2003). "A large percentage of gastric cancer cell lines express EGF-R, and gastric cancer cells grow in response to EGF/transforming growth factor-α (TGF-α) activation of EGF-R in an autocrine loop." (PMID 12618892, 2003). "Expression of EGF and its receptor has been found to correlate with prognosis in patients with gastric cancer." (PMID 12618892, 2003). "In this study, we examined NRP-1 and EGF-R expression in human gastric cancer cell lines and evaluated the effect of EGF on NRP-1 and VEGF expression." (PMID 12618892, 2003). "For example, in gastric cancer, ATXN2L expression is upregulated by EGF, which activates the PI3K/AKT signaling pathway, promoting epithelial-mesenchymal transition (EMT), migration, and invasion, all associated with a poor prognosis in gastric cancer." (PMID 39039334, 2024). "The signal transduction in gastric cancer cells is very complex with numerous active interacting pathways, including EGF, Wnt, TGFβ, and other ligands that activate cascade reactions and participate in cell cycle regulation, proliferation, differentiation, and other physiological processes." (PMID 36674593, 2023). "Interestingly, another study showed NEDD4 to be important in gastric cardia adenocarcinoma (GCA) metastasis, as the shRNA-mediated NEDD4 decrease in AGS and N87 gastric cancer cells impairs basal and EGF-stimulated cell invasion and migration." (PMID 36293239, 2022). "In addition, ATXN2L promotes cell invasiveness and oxaliplatin resistance and can be upregulated by EGF via PI3K/Akt signaling in gastric cancer." (PMID 35122570, 2022). "In addition, ATXN2L expression was upregulated by epidermal growth factor which promotes gastric cancer cell invasion and drug resistance." (PMID 36412907, 2022). "As downregulation of PTEN decreases anticancer effects in various tumors, we speculated that the PTEN-mediated EGF/PI3K signaling pathways is responsible for the gastric cancer cell apoptosis and cell migration." (PMID 34824590, 2021). "This suggested that exogenous EGF stimulation may result in enhancing the shedding of endogenous EGFR ligands in gastric cancer as observed in HNSCCs." (PMID 34658851, 2021). "Furthermore, evodiamine inhibits gastric cancer cells' directional migration by inhibiting PTEN-mediated EGF/PI3K signaling pathways." (PMID 34824590, 2021).
gastric cancer (continued). "The fact that Akt phosphorylation after MET inhibition is more efficiently restored by HRG treatment of gastric cancer cells than by EGF treatment is in line with previous findings and indicates that PI3K-Akt signaling is of particular importance for survival signaling in gastric cancer cells." (PMID 33374770, 2020). "In vitro experiments, Takaishi 26 added the selected CD44 positive gastric cancer cell into the serum-free medium containing EGF and bFGF, and they could form spherical clones after a few weeks." (PMID 32788883, 2020). "High expression of CMTM3 might correlate with favorable prognosis in gastric cancer, which not only inhibits the EGF-mediated tumorigenicity by promoting Rab5 activity, but also suppresses metastasis of gastric cancer via the STAT3/Twist1/EMT pathway." (PMID 33282744, 2020). "Similarly, a previous study also reported that only the MEK1/2/ERK1/2 pathway was involved in EGF-induced MMP13 mRNA expression in gastric cancer cells." (PMID 31635309, 2019). "In gastric cancer, EGF-induced AQP3 upregulation enhances the mesenchymal transformation." (PMID 29922644, 2018). "In view of this, our studies in gastric cancer have shown that DENND1A exerts GEF action during the activation of Rab35 stimulated by EGF, and through its interaction with Grb2, it can regionally recruit activated Rab35 and then promote the migration of tumor cells." (PMID 30524285, 2018). "Research on the effects of curcumin in other cancers such as gastric cancer, in which EGF-induced AQP3 up-regulation occurs, might further understanding of the role of AQP3 in cell migration and invasion." (PMID 29922644, 2018). "At the same time, EGF-DENND1A-Rab35 signaling pathway with DENND1A as a regulatory center may also become a new target for the treatment of gastric cancer." (PMID 30524285, 2018). "In this study, we analysed the involvement of the HER receptor ligands amphiregulin (AREG), epidermal growth factor (EGF), heparin-binding epidermal growth factor (HB-EGF) and transforming growth factor alpha (TGFα) in the responsiveness of gastric cancer cell lines to cetuximab and trastuzumab." (PMID 27933395, 2017). "On the other hand, Wnt5a is a potential suppressor of EMT in gastric cancer, wherein epidermal growth factor (EGF) activation of EMT required suppression of Wnt5a expression through activating ADP-ribosylation factor (Arf6), which binds to and represses the Wnt5a promoter." (PMID 27571105, 2016). "Whether GALNT2 also suppresses EGF-induced phenotypes in gastric cancer cells requires further study." (PMID 26848976, 2016). "We hypothesized that P-ERK might also be involved in the down-regulation of Wnt5a in gastric cancer cells in response to EGF." (PMID 25779663, 2015). "When gastric cancer cells receive signals from their microenvironment, such as EGF, TGF-β and hypoxia, cells may lose cell-cell junction, and gain migratory and invasive properties, providing them a distinct advantage in tumor progression and metastasis." (PMID 25779663, 2015). "Although Wnt5a transcription can by modulated by multiple mechanisms, such as Hedgehog and TGF-β signaling cascades, it remains unclear whether and if so, how EGF can regulate Wnt5a in gastric cancer cells." (PMID 25779663, 2015). "Moreover, gastric cancer patients with synchronous expression of EGF and EGFR have been reported to have a poor prognosis." (PMID 25729328, 2014). "Furthermore, we have shown that depletion of Nedd4-1 by shRNA in gastric cancer cells impairs both the basal and EGF-stimulated cell migration and invasion, indicating that Nedd4-1 plays a “driver” role in metastasis of GCA." (PMID 25395181, 2014). "Therefore, EGF has been considered to play a pivotal role in the occurrence and malignant progression of gastric cancer." (PMID 25729328, 2014).
gastric cancer (continued). "Decreased core-fucosylation in gastric cancer might be associated with lower core-fucosylation of EGFR, and thus with reduced activation of EGF-induced phosphorylation of the EGFR pathway." (PMID 24732908, 2014). "In particular, Nedd4-1 mediates EGF-dependent gastric cancer cell invasion and migration, suggesting that Nedd4-1 may participate in EGFR-mediated tumor metastasis signaling." (PMID 25395181, 2014). "In the present study, we observed that the EGF +61A/G polymorphism presented a risk factor for gastric cancer in Asian populations, but not in Caucasian populations." (PMID 25729328, 2014). "Additionally, a study on human gastric cancer has shown that EGF stimulates uPAR expression via the ERK pathway, sequentially increasing cell invasion." (PMID 26889270, 2013). "The activation of EGFR could have an important role for the cell proliferation and the inhibition of apoptosis, indicating that the SN38-induced activation of the EGF/EGFR may be involved in the resistance of gastric cancer cells to irinotecan." (PMID 21997136, 2011). "Notably, advanced gastric cancer patients with EGFR expression in their tumours together with low serum levels of the ligands EGF and transforming growth factor-α showed better response in one study." (PMID 22152101, 2011). "The inhibition of Hsp90 has been shown to impair EGF-mediated signalling in gastric cancer cells." (PMID 19142186, 2009). "Bombyx mori carboxypeptidase inhibitor can inhibit the rapid proliferation of gastric cancer cells induced by the addition of EGF, which indicates that the inhibitory activity of silkworm carboxypeptidase inhibitor is likely related to the downstream-related pathways initiated by EGF/EGFR." (PMID 36674593, 2023). "Therefore, the main purpose of this study is to observe the changes of Rab35 activity and its relationship with gastric cancer cell migration stimulated by EGF and to determine what kind of GEF is involved in the changes of Rab35 activity in gastric cancer cells and its possible mechanism." (PMID 30524285, 2018). "However, we found that PKM2 could also regulate the activity of the EGF/EGFR signaling pathway in gastric cancer cells." (PMID 23840737, 2013). "Previous studies have demonstrated that H. pylori infection increased EGF protein and epidermal growth factor receptor (EGFR) mRNA expression in patients with chronic active gastritis, gastric ulcers, duodenal ulcers, and gastric cancer." (PMID 39857676, 2025). "In view of the relationship between the Wnt signaling pathway and gastric cancer, we identified the prognostic five genes signatures related to the Wnt pathway in this study, including CPZ, CTHRC1, DKK1, EGF, and GPC." (PMID 40296906, 2025). "further demonstrated that PRKG1 inhibits the epidermal growth factor‐induced MAPK/ERK signalling pathway, reducing the invasive and proliferative capabilities of gastric cancer cells, suggesting PRKG1 as a potential therapeutic target." (PMID 39783847, 2025). "CMTM3 has been reported defective in gastric cancer, and overexpression of CMTM3 inhibited cell migration mediated by EGF signaling." (PMID 39948411, 2025). "We confirmed that the silkworm carboxypeptidase inhibitor inhibited the expression of c-Myc through the MAPK/ERK pathway initiated by EGF/EGFR, thereby affecting the related cyclins and inhibiting the proliferation of gastric cancer cells." (PMID 36674593, 2023). "As a biologically active ingredient, it can inhibit the expression of the proto-oncogene c-Myc by affecting the MAPK/ERK pathway initiated by EGF/EGFR, thereby inhibiting the proliferation of gastric cancer cells." (PMID 36674593, 2023). "A selection of gastric cancer cell lines (Hs746T, MKN1, MKN7 and NCI-N87) was treated with EGF, cetuximab, trastuzumab or afatinib for a period of 4 or 24 h." (PMID 35264144, 2022). "It was also shown that NEDD4 mediates EGF-dependent AGS and N87 gastric cancer cell line invasion and migration via EGFR-mediated metastasis signaling." (PMID 36293239, 2022).